CHP1 (calcineurin like EF-hand protein 1)
Description:
Calcium-binding protein involved in different processes such as regulation of vesicular trafficking, plasma membrane Na(+)/H(+) exchanger and gene transcription. Involved in the constitutive exocytic membrane traffic. Mediates the association between microtubules and membrane-bound organelles of the endoplasmic reticulum and Golgi apparatus and is also required for the targeting and fusion of transcytotic vesicles (TCV) with the plasma membrane. Functions as an integral cofactor in cell pH regulation by controlling plasma membrane-type Na(+)/H(+) exchange activity. Affects the pH sensitivity of SLC9A1/NHE1 by increasing its sensitivity at acidic pH. Required for the stabilization and localization of SLC9A1/NHE1 at the plasma membrane. Inhibits serum- and GTPase-stimulated Na(+)/H(+) exchange. Plays a role as an inhibitor of ribosomal RNA transcription by repressing the nucleolar UBF1 transcriptional activity. May sequester UBF1 in the nucleoplasm and limit its translocation to the nucleolus. Associates to the ribosomal gene promoter. Acts as a negative regulator of the calcineurin/NFAT signaling pathway. Inhibits NFAT nuclear translocation and transcriptional activity by suppressing the calcium-dependent calcineurin phosphatase activity. Also negatively regulates the kinase activity of the apoptosis-induced kinase STK17B. Inhibits both STK17B auto- and substrate-phosphorylations in a calcium-dependent manner.
Synonyms: CHP; Sid470p; SLC9A1BP; p22; p24; SPAX9
Tractability: Small molecule: a structure with a bound ligand is known. Antibody: UniProt places it where antibodies can reach, with high confidence; its Gene Ontology location is reachable by antibodies, with high confidence. PROTAC: ubiquitination databases record sites on it; its protein half-life has been measured.
Gene: Protein-coding gene on chromosome 15 (41,230,824 to 41,281,888, forward strand). Ensembl gene ENSG00000187446.
Subcellular location: Nucleus; Cytoplasm; Cytoplasm, cytoskeleton; Endomembrane system; Endoplasmic reticulum-Golgi intermediate compartment; Endoplasmic reticulum; Cell membrane; Membrane
Subcellular location (Human Protein Atlas): Vesicles
Pathways (Reactome):
Metabolism: Hyaluronan degradation
Gene Ontology:
Molecular function: calcium ion binding; calcium-dependent protein binding; protein binding; kinase binding; microtubule binding; potassium channel regulator activity; sodium:proton antiporter activity
Biological process: intracellular sodium ion homeostasis; negative regulation of calcineurin-NFAT signaling cascade; negative regulation of phosphatase activity; negative regulation of protein import into nucleus; positive regulation of phospholipid biosynthetic process; positive regulation of sodium:proton antiporter activity; regulation of intracellular pH; cellular response to acidic pH; cytoplasmic microtubule organization; membrane docking; membrane fusion; membrane organization; microtubule bundle formation; negative regulation of protein autophosphorylation; negative regulation of protein kinase activity; negative regulation of protein phosphorylation; negative regulation of protein ubiquitination; positive regulation of glycoprotein biosynthetic process; positive regulation of protein targeting to membrane; positive regulation of protein transport; potassium ion transport; protein export from nucleus; protein stabilization; small GTPase-mediated signal transduction; regulation of calcineurin-NFAT signaling cascade; and 2 more
Cellular component: cation-transporting ATPase complex; extracellular exosome; focal adhesion; membrane; plasma membrane; basolateral plasma membrane; cytoplasm; endomembrane system; endoplasmic reticulum; endoplasmic reticulum-Golgi intermediate compartment; Golgi membrane; microtubule cytoskeleton; nucleus; transport vesicle; cytoskeleton; membrane raft; transporter complex
Genetic constraint (gnomAD): Loss-of-function variants: 8 observed, 20.9 expected, observed/expected ratio (o/e) 0.38, 90% interval 0.22 to 0.69. The upper end of that interval is the gene's LOEUF score, 0.69, which puts it in group 2 of 6, group 1 being the genes least tolerant of losing a copy. Missense variants: 149 observed, 225.5 expected, observed/expected ratio (o/e) 0.66, 90% interval 0.58 to 0.76. Synonymous variants: 83 observed, 80.18 expected, observed/expected ratio (o/e) 1.04, 90% interval 0.87 to 1.24.
Homologues: Orthologues: chimpanzee CHP1 (100% identical), guinea pig CHP1 (99% identical), mouse Chp1 (99% identical), rabbit CHP1 (99% identical), dog CHP1 (98% identical), pig CHP1 (98% identical), rat LOC120102456 (98% identical), rat Chp1 (92% identical), macaque CHP1 (73% identical), zebrafish chp2 (62% identical), Drosophila melanogaster elm (58% identical), Caenorhabditis elegans chpf-1 (56% identical), and 5 more. Paralogues in human: CHP2 (61% identical), PPP3R1 (40% identical), PPP3R2 (37% identical), TESC (36% identical), CIB2 (25% identical), CIB3 (23% identical), CIB1 (23% identical), CIB4 (22% identical).
Diseases named in the same sentence as CHP1 in open-access papers:
CHP1 is named in the same sentence as 25 diseases in open-access papers, as found by Europe PMC text mining. Sharing a sentence is not in itself a finding about the gene and the disease. The quoted sentences say what the papers report.
Ataxia (3 papers, 2019 to 2021). Ataxia refers to impaired coordination of voluntary muscle movement. "PLS3 overexpression increases membrane targeting of NHE1, an important binding partner of CHP1 that is also associated with ataxia when mutated, at an early disease stage." (PMID 34023917, 2021). "Instead in several neuromuscular disorders, such as spinal muscular atrophy (SMA), amyotrophic lateral sclerosis (ALS) and CHP1-associated ataxia, PLS3 overexpression acts as a protective modifier." (PMID 34023917, 2021). "Nevertheless, this study highlights the involvement of PLS3 OE as a cross-disease modifier for neurodegenerative diseases, including SMA and CHP1-associated ataxia." (PMID 31607845, 2019). "In conclusion, this study reveals that PLS3 OE is a disease modifier for ataxia caused by Chp1-depletion." (PMID 31607845, 2019). "The Chp1 mutant mouse model was originally reported to develop cerebellar ataxia caused by Purkinje neuron degeneration in the cerebellum." (PMID 31607845, 2019). "Thus, PLS3 overexpression has a moderate protective effect on ataxia caused by Chp1 depletion and demonstrates its potential as a cross-disease modifier." (PMID 34023917, 2021). "Indeed, recently we reported that PLS3 overexpression is beneficial in CHP1-related ataxia in mice that carry biallelic Chp1 mutation." (PMID 32938453, 2020). "In this study, we aimed to determine whether PLS3 is a cross-disease modifier for ataxia caused by Chp1 mutation in mice." (PMID 31607845, 2019). "Since, it has been shown that PLS3 directly interacts with CHP1, and CHP1 depletion causes ataxia in the vacillator mouse model, we hypothesized that PLS3 OE may improve the ataxic phenotype in vivo." (PMID 31607845, 2019). "Since PLS3 has been shown to directly interact with CHP1, in this study we investigated whether PLS3 is a cross-disease modifier for ataxia caused by Chp1 mutation in mice." (PMID 31607845, 2019). "Importantly, in the context of SMA, about 50% CHP1 reduction was beneficial, whereas in case of ataxia, CHP1 levels were dramatically reduced, causing impaired NHE1 maturation and imbalance of pH homeostasis." (PMID 31607845, 2019). "Thus, we speculate that the effects of CHP1 reduction on ameliorating SMA pathology or causing ataxia mostly rely on different functions and dosages of CHP1." (PMID 31607845, 2019). "Among them, PLS3 directly interacts with calcineurin like EF-hand protein 1 (CHP1), whose loss-of-function results in ataxia." (PMID 31607845, 2019). "Consequently, loss-of-function mutations and diminished levels of CHP1 lead to altered NHE1 maturation, causing defective pH homeostasis in Purkinje neurons, thereby leading to axon degeneration and subsequent cell death and eventually to ataxia." (PMID 31607845, 2019).
breast carcinoma (3 papers, 2020 to 2023). "CHP1 is expressed ubiquitously in all tissues, whereas CHP2 is expressed in the small intestine and several cancers, including hepatic carcinoma, leukemia, breast cancer, and ovarian cancer." (PMID 32365487, 2020).
hepatocellular carcinoma (3 papers, 2020 to 2025). A malignant tumor that arises from hepatocytes. "A recent study in hepatocellular carcinoma (HCC) identified a five-gene natural killer cell-related signature (NKRLSig), which included CHP1, and demonstrated that patients in the low-risk group exhibited improved responses to immunotherapy." (PMID 40723891, 2025).
autosomal recessive spastic ataxia (1 paper, 2021). Autosomal recessive form of spastic ataxia. "Biallelic mutations in CHP1 cause autosomal recessive spastic ataxia (SPAX9; MIM 618438) in humans and mice." (PMID 34023917, 2021).
Cerebellar atrophy (1 paper, 2024). Cerebellar atrophy is defined as a cerebellum with initially normal structures, in a posterior fossa with normal size, which displays enlarged fissures (interfolial spaces) in comparison to the foliae secondary to loss of tissue. "In conclusion, Chp1 impacts on the biogenesis and also on the post-translational quality control of eEF1A F98C mutant derived from patients with EEF1A2-linked cortical/cerebellar atrophy." (PMID 38360885, 2024).
cholangiocarcinoma (1 paper, 2020). A carcinoma that arises from the intrahepatic biliary tree (intrahepatic cholangiocarcinoma) or from the junction, or adjacent to the junction, of the right and left hepatic ducts (hilar cholangiocarcinoma). "However, unlike the expression of TESC, we found that CHP1 is dominantly expressed in normal tissues and that the expression of CHP2 does not differ significantly between cholangiocarcinoma and adjacent non-tumor tissues." (PMID 32365487, 2020).
chronic myeloid leukemia (1 paper, 2025). "Imatinib mesylate, a clinically approved tyrosine kinase inhibitor (TKI) for chronic myeloid leukemia and gastrointestinal stromal tumors, is known to interact with transferrin and may be repurposed based on its newly predicted affinity for CHP1." (PMID 40723891, 2025).
co-infection (1 paper, 2025). "Four strains (CHP1, CHP2, CHP3, and CHP4) of H. pylori from gastric tissues of patients, who exhibited disparate clinical symptoms and tumor types, were isolated and tested for co-infection." (PMID 40833108, 2025). "Interestingly, the results showed that each H. pylori strain (CHP1, CHP2, CHP3, and CHP4) infection alone or co-infection with EBV led to reduced growth of NGOs, when compared to the mock group." (PMID 40833108, 2025).
epidermoid carcinoma (1 paper, 2020). "In order to test if the function of CHP-1 in the EGFR signaling pathway is conserved in mammals, we inactivated the CHP-1 homolog CHORDC1 in human A431 epidermoid carcinoma cells, which express high levels of the wild-type EGFR and undergo a phenotypic switch in response to EGF stimulation." (PMID 32053105, 2020).
epilepsy (1 paper, 2024). A brain disorder characterized by episodes of abnormally increased neuronal discharge resulting in transient episodes of sensory or motor neurological dysfunction, or psychic dysfunction. "NHE1, the principal target of CHP1, confers resistance to apoptosis and loss of NHE1, a neuronal plasma membrane constituent of the hippocampus and cortex, increases central nervous system excitability and produces epilepsy." (PMID 38166692, 2024).
prostate carcinoma (1 paper, 2017). A carcinoma that arises from epithelial cells of the prostate gland. "The underexpression of REIC/Dkk-3 in CHP-1 suggests that the lack of this protein causes the androgen-independency in canine prostate cancer." (PMID 28599655, 2017). "Therefore, CHP-1 may have similar characteristics to human androgen-independent prostate cancer cells, e.g. PC3." (PMID 28599655, 2017).
sarcoma (1 paper, 2026). A usually aggressive malignant neoplasm of the soft tissue or bone. "Serum deprivation did not significantly alter CHP1 or CHP2 protein expression; however, silencing of CHP2 reduced NHE1 activity under serum-deprived conditions and significantly decreased migration and proliferation in both sarcoma cell lines." (PMID 41749826, 2026).
tumor (7 papers, 2020 to 2026). "Low CHP1 expression, older age, and advanced tumor stage contributed to higher risk scores, which were inversely associated with survival probability." (PMID 40723891, 2025). "An in-depth analysis of the molecular mechanisms underlying CHP1 function in ccRCC revealed that CHP1 might modulate amino acid transmembrane transport, a process essential to tumor cell survival and metabolism." (PMID 40723891, 2025). "Focusing on CHP1, we observed that its expression was predominantly restricted to epithelial cells and significantly decreased in tumor tissues." (PMID 40723891, 2025). "The pseudotime trajectory analysis revealed that CHP1 is predominantly expressed in early-stage tumor cells, with its expression gradually declining along the developmental timeline, which is consistent with its potential role in tumor suppression." (PMID 40723891, 2025). "A comparative analysis revealed that five sodium ion transport-related genes—FXYD2, ANK3, ATP1A1, PRSS8, and CHP1—were significantly downregulated in malignant cells, implicating their potential involvement in tumor suppression." (PMID 40723891, 2025). "To evaluate CHP1 protein expression in ccRCC, we conducted IHC on 80 pairs of tumor and matched adjacent kidney tissues (160 samples in total) and Western blotting on the ccRCC cell lines." (PMID 40723891, 2025). "These roles underscore the importance of CHP1 in energy storage, membrane formation, and possibly tumor biology." (PMID 40723891, 2025). "To substantiate these observations, we transfected tumor cell lines with 3xFlag-CHP1-NmyrMT or control plasmids." (PMID 40605065, 2025). "Concurrently, the NMT1 inhibitor PCLX-001, at a concentration of 0.1 μmol/L, reduces PD-L1 membrane localization on tumor cells by inhibiting CHP1 myristoylation, decreasing PD-L1 availability to interact with PD-1 on T cells." (PMID 40605065, 2025). "Therefore, this study aimed to investigate the expression dynamics, functional role, and molecular mechanism of CHP1 in ccRCC using scRNA-seq, offering new insights into both tumor biology and potential therapeutic strategies." (PMID 40723891, 2025). "Notably, CHP1 expression was predominantly observed in early-stage tumor cells and gradually diminished along the pseudotime axis, indicating a potential role of CHP1 in early-stage tumor biology and differentiation." (PMID 40723891, 2025). "In vivo, CHP1 or TMEM87A knockout significantly suppressed orthotopic tumor growth and metastasis in NSG mice, indicating a role in overall tumor progression beyond metastasis alone." (PMID 42258092, 2026). "In our previous work, we developed a glycosylation–tumor microenvironment (GLY/TME) classifier using 15 glycosylation-related genes, where CHP1 emerged as a favorable prognostic marker in HCC." (PMID 40723891, 2025). "Moreover, in hypoxic tumor cells, the CHP1 N-myristoylation level increased without significant changes in its expression, which was consistent with the overall increase in the cellular N-myristoylation level." (PMID 40605065, 2025). "We observed that 4/7 FAS genes, GPAT4, CHP1, PCGF1, and GPI, show significant, negative hazard ratios (HR), consistent with a tumor suppressor signature, and that no other gene from our set shows a negative HR." (PMID 34764293, 2021).
cancer (6 papers, 2017 to 2025). A tumor composed of atypical neoplastic, often pleomorphic cells that invade other tissues. "Although CHP1 has been implicated in multiple physiological processes, its role in cancer, particularly in ccRCC, remains largely unexplored." (PMID 40723891, 2025). "The NMT1 inhibitor low-dose PCLX-001 blocks CHP1 myristoylation, disrupting excessive PD-L1 membrane localization and attenuating cancer immune suppression." (PMID 40605065, 2025). "Also, many targeted genes, such as ZEB1, SOX5, AKAP1, CHP1, CNBP, VEGFR, and MAGT1, play a vital function in the cell shape, movement, invasion, adhesion, and polarity formation, so as to involve in many kinds of diseases such as malignant tumors, wound healing, and so on." (PMID 32547593, 2020).
neurodegenerative disease (2 papers, 2017 to 2019). A disorder of the central nervous system characterized by gradual and progressive loss of neural tissue and neurologic function. "Chp1 was required for axon degeneration in many neurodegenerative diseases, and Chp2, the homologous gene of Chp1, could enhance the oncogenic potential of HEK293 cells through activating the calcineurin/nuclear factor signaling pathway in activated T cells." (PMID 29383134, 2017).
CHP1 also shares sentences with these, for which no sentence is quoted: infection (3 papers); Hypertension (2); spinal muscular atrophy (2); amyotrophic lateral sclerosis (1); cerebellar ataxia (1); Clear Cell Renal Cell Carcinoma (1); gastrointestinal stromal tumor (1); glioma (1); leukemia (1); ovarian carcinoma (1).